MTOR (mechanistic target of rapamycin kinase)
Diseases named in the same sentence as MTOR in open-access papers (continued):
Sharing a sentence is not in itself a finding about the gene and the disease.
melanoma (continued). "Indeed, when primary cells from lungs of active mice were treated with the mTOR inhibitor rapamycin and co-cultured with B16 melanoma cells, the metabolic advantage was lost, and tumor growth was resumed." (PMID 38164270, 2024). "Among them, PI3K/AKT/mTOR pathway regulates the invasion and metastasis process of melanoma upon activation by Piezo1, and the expression of EMT-related genes and invasion and metastasis-related genes (MMP2 and MMP9) in cells changes with the alteration of Piezo1 expression." (PMID 38690080, 2024). "Overall, targeting PI3K, AKT, and mTOR proteins by a specific inhibitor may offer a therapeutic option for the treatment of different tumor types including melanoma." (PMID 38334632, 2024). "The PI3K/Akt/mTOR signaling axis is also the target for inhibiting the metastasis of melanoma." (PMID 38674007, 2024). "Thus, targeting the Fyn/CD133/AKT/mTOR axis likely possesses a therapeutic impact for melanoma treatment." (PMID 38334632, 2024). "Consequently, targeting the PI3K/Akt/mTOR pathway has emerged as a promising therapeutic strategy for melanoma treatment." (PMID 39200315, 2024). "Additionally, the lipid phosphatase activity of phosphatase and tensin homolog (PTEN) suppresses fos-related antigen 1 (FRA1) expression through the AKT/mTOR signaling pathway, thereby reducing melanoma cell proliferation, invasion, and tumor growth." (PMID 38921444, 2024). "In this process, AKT acts as a molecular switch that is linked with the elevated activation of mTOR and S6K1, enhancement of angiogenesis, and the accumulation of reactive oxygen species (ROS) that can enhance further aggressiveness and metastasis in melanoma." (PMID 38334632, 2024). "Moreover, the protein kinase B/mammalian target of rapamycin (AKT/mTOR) pathway is activated in part through HIFs, and the pharmacological inhibition of mTOR with rapamycin inhibits melanoma growth in mice." (PMID 36901857, 2023). "Pre-clinical data by several groups have suggested that combining BRAF/MEK inhibitors with PI3K/mTOR inhibitors may overcome resistance in BRAF mutant melanomas." (PMID 36983983, 2023). "In this study, p‐AKT1 and p‐mTOR levels were dramatically elevated in melanoma tissues, indicating that the AKT/mTOR signalling pathway might be involved in regulating melanoma progression." (PMID 37539493, 2023). "Moreover, neural cell adhesion molecule (NCAM) knockdown inhibits the metastasis of human melanoma cells via the Src/Akt/mTOR/cofilin pathway." (PMID 37511481, 2023). "Oleacein, an extra-virgin olive oil polyphenol, induces antiproliferative and apoptotic effects in melanoma cells by upregulating miR-193a-3p, miR-193a-5p (targeting mTOR), miR-34a-5p, and miR-16-5p (targeting mTOR) and downregulating miR-214-3p (targeting BAX)." (PMID 36835100, 2023). "Several types of mTOR inhibitors, the first- and second-generation, have been examined in various cancer models, including breast, lung, gastric, colorectal, prostate, head and neck, lymphoma, urinary bladder, renal, and melanoma." (PMID 37097377, 2023). "Genetic alterations or ultraviolet (UV) exposure results in the dysregulation of the PI3K/Akt/mTOR pathway in melanocytes, basal cells, squamous cells, or Merkel cells, which leads to the development of melanoma, basal cell carcinoma, cutaneous squamous cell carcinoma, or Merkel cell carcinoma." (PMID 36980552, 2023). "Melanoma cells are characterized by a low sensitivity to apoptosis associated with high expression of antiapoptotic proteins of the BCL-2 family, loss of activity of Apaf-1 factor and up-regulation of the PI3K/AKT/mTOR pathway." (PMID 36674631, 2023). "mTOR is an activated protein found in 73% of human melanoma cell lines." (PMID 36676131, 2023). "Finally, we used DMEA to test data sets from human CD34+ cells treated with the glucocorticoid agonist dexamethasone and A2058 melanoma cells treated with the PI3K/mTOR inhibitor BEZ235." (PMID 37226094, 2023).
melanoma (continued). "mTOR pathway dysregulation leads to uncontrolled epidermal-proliferation and -inflammation, especially in psoriasis, atopic dermatitis, pemphigus, acne, cutaneous T cell lymphoma, and melanoma." (PMID 37495626, 2023). "The subject of this research was the effect of protein kinase inhibitors involved in the AKT, MEK, and mTOR kinase signaling pathways on the expression of pro-survival proteins, activity of caspase-3, proliferation, and induction of apoptosis in melanoma cells." (PMID 37097377, 2023). "Therefore, p38 plays a tumor suppressive role in NRAS-mutant melanomas at least partially through the mechanism of mTOR upregulation, suppressed autophagy, and reduced actin polymerization." (PMID 36765834, 2023). "The merit of FIR-preconditioning might influence MITF-Akt-mTOR-exosome trajectory both in normal cells and the tumor microenvironment in melanoma." (PMID 37123908, 2023). "Furthermore, SNAI2-knockdown was also reported to suppress the activation of the PI3K/Akt/mTOR pathway, thereby suppressing the development of melanoma." (PMID 35654777, 2022). "Both mTOR complexes stimulate cancer cell metabolic functions by promoting glucose metabolism, energy production, lipid, and protein synthesis, which collectively fuel the expansive growth of malignant melanoma." (PMID 36077374, 2022). "A recent report showed a link between cofilin phosphorylation and SRC/AKT/mTOR pathway in melanoma." (PMID 35882839, 2022). "Another important pathway commonly upregulated in melanomas is that of PI3K/AKT/mTOR which regulates cell proliferation, cellular response during stress and quiescence, contributing to tumor growth, metastasis and angiogenesis induction in melanomas." (PMID 35495634, 2022). "Here, we investigated the antitumor effects of the mTOR inhibitor PTS on melanoma cells." (PMID 36077992, 2022). "Indeed, in vitro and in vivo investigations of the effect of this compound against melanoma cells have demonstrated its important potency as an excellent PI3K/mTOR dual inhibitor." (PMID 36428613, 2022). "Pathway analysis with the differentially down-regulated phosphor-motifs depicts receptor tyrosine kinases, inflammatory interleukins, ERK1/2, AKT, and mTOR as the major signaling cascades that are affected after treatment of melanoma cells with 3, 3′- (3, 5-DCPBC) for a period of 4 h." (PMID 35208960, 2022). "Furthermore, the upregulation of the pentose phosphate pathway and lipogenesis were reversed by the NCTD treatment possibly via the mTOR pathway in Vem-resistance melanoma." (PMID 36034784, 2022). "Rg3 also suppressed tumor growth via modulation of the ERK/AKT/mTOR signaling pathway in melanoma." (PMID 36012338, 2022). "Therefore, considering the prominent role of mitochondria in the onset of melanoma therapeutic resistance, mTOR signaling seems to be involved in the regulation of this process at the switch between sensitivity and resistance to BRAFi/MEKi." (PMID 36077374, 2022). "Both melanoma growth and metastasis are regulated not only by intrinsic cellular mechanisms, such as the PI3K/AKT/mTOR pathway, but also by cross-talk between melanoma cells, neighboring cells, and extracellular matrix (ECM) by means of extracellular vesicles (EVs)." (PMID 35327461, 2022). "They found that although the majority of nevi bear mutations that activate the RAS/MAPK axis, the vast majority of benign lesions are negative (or modestly positive) for mTORC1 activation, whereas more than 70% of melanomas display strong mTOR-dependent S6 phosphorylation." (PMID 36077374, 2022). "However, data on the effects of combinations of mTOR inhibitors with ICI on melanoma models are currently missing." (PMID 36077374, 2022). "Moreover, numerous in vitro studies have indicated that resveratrol is able to induce autophagy, inhibiting the Akt/mTOR pathway in B16F10 melanoma cells." (PMID 35458783, 2022).
melanoma (continued). "Moreover, the study indicated that AKT and mTOR, as well as their downstream product, p70S6K, are present and active in canine melanoma cells." (PMID 36077992, 2022). "By mutating the tyrosine sites of ITIM and ITSM, it was determined that melanoma-PD-1-driven tumorigenesis required the interactions between melanoma-PD-1 and host/melanoma-PD-L1 to initiate the PD-1 intracellular signaling via the mTOR pathway." (PMID 35663968, 2022). "Moreover, primary renal cell carcinomas, melanomas and neuroendocrine tumors appear to respond well to promising potential pathway inhibitory therapies of the mTOR pathway such as everolimus." (PMID 36507516, 2022). "Recent studies provide evidence that mTOR inhibitors may represent a supplementary weapon in the quiver of melanoma treatment alongside with a combination of BRAF and MEK inhibitors." (PMID 35163615, 2022). "Moreover, NRF2 activators exhibit an anti-pigmentation effect in melanoma/melanocytes through the PI3K/AKT/mTOR/autophagy axis." (PMID 35807430, 2022). "The effects of mTOR inhibition were further evaluated in an additional panel of 29 human cancer cell lines from diverse tissue origins, including pancreatic, breast, prostate, colon, liver, lung, ovarian, cervical cancers and melanoma." (PMID 36396656, 2022). "Through a process of drug screening focusing on Ras/MAPK and PI3K/Akt/mTOR signal transduction pathways using canine mucosal melanoma cell lines and preclinical xenograft models, small molecule kinase inhibitors sapanisertib and trametinib were chosen for further evaluation as a combination." (PMID 36590793, 2022). "To further clarify whether the function of Piezo1 in regulating the malignant progression of melanoma was directly dependent on the PI3K/AKT/mTOR pathway, we treated wild-type A375 cells with the PI3K inhibitor LY294002, the Piezo1 activator Yoda1 and both." (PMID 36112948, 2022). "It is therefore plausible that the mammalian (or mechanistic) Target of Rapamycin mTOR pathway, a key sensor and effector of nutrient signaling as well as protein and lipid biosynthesis, plays an important role in melanoma progression, by itself or through a crosstalk with the ISR." (PMID 35912100, 2022). "For instance, activation of the mTOR signaling pathway has been also explored in canine melanoma as well as in the human disease, and studies in canine melanoma cell lines have demonstrated activation of this pathway along with the inhibitory efficacy of Rapamycin and other drugs." (PMID 36686160, 2022). "Activation of the PI3K/AKT/mTOR pathway facilitates melanoma resistance to BRAF and MEK inhibition." (PMID 36497341, 2022). "We also identified new mutations in the CDK and PI3K/AKT/mTOR pathways in clear cell RCC brain metastasis tumors, while a melanoma brain metastasis also showed a single new CDKN1B gene mutation, suggesting the potential for CDK inhibitor therapy in these patients." (PMID 36507516, 2022). "Furthermore, recent studies reveal the implication of signaling PI3K/mTOR axis in the pathogenesis of melanoma." (PMID 35163615, 2022). "Finally, recent data on the prime role of the tyrosine kinases SRC and the AKT/mTOR axis in melanoma progression highlights the unique implication of 3, 3′- (3, 5-DCPBC) as a promising small molecule drug candidate." (PMID 35208960, 2022). "Furthermore, insulin can weaken the sensitivity of melanoma cells to DTIC by triggering the phosphoinositide 3-kinase (PI3K)/mTOR signaling pathway." (PMID 34926249, 2021). "However, another study emphasized the potential role of PI3K/Akt/mTOR axis hyperactivity in brain metastases of melanomas." (PMID 35029792, 2021). "YM1 produced by macrophages may promote the expression of functional xCT via mTOR signaling in melanoma while mTOR inhibitors, including rapamycin, may promote the sensitivity of tumor cells to γ-ray-induced ROS via the functional attenuation of xCT in tumors." (PMID 33959512, 2021).
melanoma (continued). "Inhibition of mTOR by rapalogs, such as rapamycin and everolimus combined with carboplatin chemotherapy may have activity in canine melanoma." (PMID 34895222, 2021). "Temsirolimus, an mTOR inhibitor, could enhance anti-tumor immune responses in melanoma and renal cell cancer mouse models when used with cancer vaccines." (PMID 33807608, 2021). "Upregulation of the PI3K/AKT/mTOR pathway has been observed in canine malignant melanoma and may represent a potential target for therapy." (PMID 34895222, 2021). "Hence, the blockage of mTORC1 by rapamycin strengthens the effectiveness of our candidate in the blockage of the ERbB/PI3K/AKT/mTOR pathway and potentially arrests the initiation of a drug resistance mechanism in melanoma cells." (PMID 33672955, 2021). "Recent studies have shown that rapamycin (also called sirolimus), an mTOR inhibitor, blocks the mTOR signaling pathway leading to suppression of angiogenesis and lymphangiogenesis in melanoma, and downregulates the expression of VEGF-A/VEGFR-2 and VEGF-C/VEGFR-3." (PMID 33807778, 2021). "These synthetic small molecules were investigated as new, potential single and/or multi-kinase inhibitors of the cyclin-dependent kinase-2 (CDK2), receptor tyrosine kinases (c-KITs), and mammalian targets of rapamycin (mTOR) targets, potentially active against melanoma or non-melanoma skin cancers." (PMID 33665254, 2021). "However, the exact mechanism of RTKs for mTOR activation in different CR melanoma situation needs further in-depth study." (PMID 34304249, 2021). "Based on a report, the AKT/mTOR activation is noticeable in approximately 70% of melanoma patients." (PMID 33692796, 2021). "Notably, the mTOR pathway can also activate fatty acid oxidation pathways; thus, we explored the role of MYC and mTOR signalling in metabolic reprogramming following CDK4/6 inhibition in the context of melanoma cells." (PMID 33572972, 2021). "Evidence for PI3K pathway upregulation was found in virtually all of the NZM lines investigated, although the mechanisms by which this was achieved varied greatly, and it was found that targeting the PI3K pathway in the melanoma cells was most universally effective when done at the level of mTOR." (PMID 33549048, 2021). "In addition, it reduces phosphorylation of Akt, mTOR, microphthalmia-associated transcription factor (MITF), and p70S6K proteins in human melanoma 451Lu cells in a dose-dependent manner." (PMID 34830339, 2021). "It was hypothesized that combination treatment would inhibit the mTOR pathway, increase cellular apoptosis and decrease viability of melanoma cells." (PMID 34895222, 2021). "Importantly, there were significant inverse correlations between miR-181a/b expression and melanoma-related oncogenic pathways as mTOR and Hedgehog." (PMID 33670365, 2021). "Receptor tyrosine kinases (EGFR, HER2, PDGFRa, and FGFR in colorectal, breast, head and neck, gastric cancer, NSCLC, glioblastomas, GISTs, melanoma, etc.), PI3KCA and RAS mutation-mediated PI3K hyperactivity, as well as the loss of PTEN or TSC1/2, leading to mTOR hyperactivity in many cancers." (PMID 35029792, 2021). "Interestingly, intrinsic PD-1 signaling in melanoma cells activates downstream mTOR signaling in a PI3K/AKT-independent manner, distinct from that observed in canonical PD-1 signaling." (PMID 33593825, 2021). "Rapamycin (sirolimus) and everolimus are commercially available small molecule inhibitors that target mTOR and therefore may have anticancer activity in canine melanoma." (PMID 34895222, 2021). "Thus, the amelanotic melanoma cells appear to respond in a similar fashion to the melanotic melanoma cells, reinforcing the dependence of both subtypes of melanoma on mTOR signaling for malignant cell growth in vivo." (PMID 34331013, 2021).
melanoma (continued). "In particular, under hypoxia and normoxia, HIF-1α can increase the expression of urokinase plasminogen activator receptor (uPAR), which in turn leads to a glycolytic and invasive phenotype in melanoma cells in a EGFR-dependent manner with involvement of the PI3K/mTOR/HIF-1α pathway." (PMID 32528879, 2020). "Taken together, TM suppresses p-S6 through blunting PI3K/Akt/mTOR signaling in melanoma cells, an effect that is likely responsible for the pro-apoptotic effects observed as treatment with various inhibitors of the pathway was able to recapitulate the phenotype." (PMID 32085796, 2020). "Therefore, OA possesses the ability of a dual control in melanoma, i.e. antiapoptosis and mTOR inhibition, revealing an interesting potentiality as a novel antitumor drug scaffold." (PMID 33071785, 2020). "We hypothesized that changes induced in the endolysosomal compartment of melanoma cells in response to PIKfyve inhibition and pyridinyl imidazole compounds might interfere with mTOR subcellular localization." (PMID 32531927, 2020). "Furthermore, mTOR signaling activation markedly prevented the baicalein and baicalin-induced senescence in both human and mouse melanoma cells." (PMID 32984331, 2020). "In melanoma, PD-1 may negatively regulate melanoma cells by inhibiting downstream mTOR signaling effector molecules, indicating the crucial role of PD-1/PD-L1 in the mTOR signaling pathway." (PMID 32351559, 2020). "Similarly, mTOR inhibitor everolimus is shown to selectively target BRAF-mutant melanoma in acidic condition." (PMID 33262326, 2020). "Before analyzing the impact of pyridinyl imidazole-induced mTOR delocalization from lysosomes on the physiology of melanoma in more detail, we wanted to make sure that the compounds’ effect was not limited to A375 melanoma." (PMID 32531927, 2020). "Therefore, we considered that the inhibitory effect of Polyphyllin I on the PI3K/Akt/mTOR signaling pathway played indispensable roles in suppressing melanoma growth." (PMID 32733943, 2020). "For instance, given that mTOR inhibitor is a potent inducer of autophagy, HCQ relieved temsirolimus, a mTOR inhibitor, resistance and significantly enhanced antitumor activity with safety and acceptability in cancer patients with advanced solid tumors and melanoma." (PMID 33239065, 2020). "However, the SN-treated samples increased the level of all the mTOR pathway signaling genes, which means that SN treatment helps in autophagy regression and hence promotes melanoma progression." (PMID 32178401, 2020). "The dual targeting of BRAF and mTOR signaling pathways, which are essential for the growth of a significant proportion of melanomas, suggested that pyridinyl imidazole compounds could have a therapeutic potential in BRAF-mutated melanoma." (PMID 32531927, 2020). "It has been previously demonstrated that treatment of melanoma cells with mTOR inhibitors: rapamycin or everolimus had a significant effect on cell cycle regulation, and in consequence, proliferation as their use led to a significant reduction of the number of cancer cells." (PMID 31586300, 2020). "Moreover, mTOR expression levels were downregulated also through the increased expression of its silencing agents, miR-16-5p and miR-193a-5p, in OA-treated melanoma cells." (PMID 33071785, 2020). "G-361 melanoma cell reduction was produced because of a decrease in the extracellular pH, which results in a reduction in the intracellular glucose level with the inhibition of mTOR and EGF survival pathways and leads to autophagy activation." (PMID 32178401, 2020). "Malignant melanomas have elevated AKT phosphorylation or activated PI3K/AKT/mTOR pathways." (PMID 33371199, 2020). "The upregulation of mTOR signaling makes melanoma cells more sensitive to Everolimus, thus suggesting that ShcD depletion can potentiate the effect of combined targeted therapy in melanoma cells." (PMID 33202906, 2020).